RN7SL140P (RNA, 7SL, cytoplasmic 140, pseudogene)
Gene: Miscellaneous RNA gene on chromosome 2 (20,175,346 to 20,175,639, forward strand). Ensembl gene ENSG00000266059.
Homologues: Orthologues: chimpanzee Metazoa_SRP (94% identical), macaque Metazoa_SRP (84% identical). Paralogues in human: RN7SL1 (75% identical), RN7SL2 (75% identical), RN7SL3 (74% identical), RN7SL183P (73% identical), RN7SL5P (72% identical), RN7SL230P (72% identical), RN7SL296P (72% identical), RN7SL395P (72% identical), RN7SL732P (72% identical), Metazoa_SRP (72% identical), RN7SL118P (71% identical), RN7SL357P (71% identical), and 701 more.